TERT (telomerase reverse transcriptase)
Diseases named in the same sentence as TERT in open-access papers (continued):
Sharing a sentence is not in itself a finding about the gene and the disease.
tumor (continued). "For example, while one tumor region may show sensitivity to a specific therapy targeting EGFR amplification, another region might harbor mutations like TERT promoter alterations that drive treatment resistance." (PMID 39767571, 2024). "Therefore, it is reasonable to claim that in a progressing virtual tumour, the wild-type, TERT-rearranged, and ATRX-inactivated clones behaved identically on average." (PMID 39715281, 2024). "Furthermore, IDH1 and TERT mutations, 1p19q codeletion and MGMT methylation status were shown to be independently associated with tumour growth, providing molecular basis for the worse outcome." (PMID 38802734, 2024). "Approximately 90% of human tumor cells have an upregulation of TERT activity." (PMID 39273661, 2024). "Whole exome sequencing results revealed that such EV-DNA carried tumor-specific genetic mutations, including those occurring on known oncogenes and tumor suppressor genes in neuroblastoma (ALK, CHD5, SHANK2, PHOX2B, TERT, FGFR1, and BRAF), and represented the entire exome." (PMID 39402599, 2024). "No BRAF, NRAS, NF1 or TERT promoter mutations were detected, though all tumor samples harbored additional mutations." (PMID 38903495, 2024). "We successfully immortalized one RB tumor cell line (T14) and one RB derived stromal cell line (T18) in RB culture medium by lentiviral transduction of TERT or LargeT, included microsatellite analysis for future cell line authentication and subsequently characterized both of them." (PMID 39695086, 2024). "We found MYCN amplifications in 23 tumors (20%), rearrangements affecting the TERT locus in 19 tumors (17%) and ATRX mutations in 12 tumors (10%), comprising 7 focal deletions, 4 missense or nonsense mutations and one tumor affected by a structural rearrangement (NBL54)." (PMID 39635126, 2024). "The study demonstrated that YLS010 has potent anti-tumor effects on acute T-lymphoblastic leukemia cells both in vitro and in vivo, It induces the mitochondrial apoptotic pathway of the cells through the dual inhibition of Trx1 and TERT." (PMID 38730567, 2024). "However, when acting as part of the telomerase holoenzyme, TERT can regulate telomere elongation, ultimately participating in tumor formation in a telomere-dependent or -independent manner." (PMID 38278800, 2024). "Presence of peritumoral edema but not age, tumor localization, TERT promoter mutation, brain invasion or WHO grading was associated with incidence of preoperative seizures, as confirmed in multivariate analysis (OR: 6.61, 95% CI: 1.18, 58.12, p = *0.049)." (PMID 38581569, 2024). "TERT silencing is considered one of the most important tumor-suppressing factors in humans." (PMID 39273661, 2024). "Further, ThyroSPEC study of the primary tumor demonstrated a TPR::NTRK1 fusion-positive tumor (without TERT promoter mutations)." (PMID 38642578, 2024). "Using these assays, we explore the regulatory mechanisms of TERT AS (i.e., inclusion of exons 7/8 or exclusion of exons 7/8) in multiple contexts (i.e., differentiation to specific cell types, specific tumor types and under different growth stresses) as they remain elusive." (PMID 37531400, 2023). "Thus, TERT not only maintains neoplasm survival through its canonical function, but it also appears to sustain tumour progression by supporting angiogenesis." (PMID 37041671, 2023).
tumor (continued). "Telomerase reverse transcriptase (TERT) has a broad yet specific range of effects that regulate normal function, but have also been implicated in tumor progression and malignant transformation." (PMID 36843111, 2023). "However, patients with TERT mutation had significantly thinner TMT (p < 0.01), and tumor localization in eloquent brain areas was associated with thicker TMT (p < 0.05) in monovariate analysis." (PMID 37727210, 2023). "However, the evidence of extra-telomeric functions of TERT, the catalytic component of telomerase, in promoting tumour growth/progression strongly supports the potential telomere length-independent therapeutic effects of TERT inhibition." (PMID 37345011, 2023). "In the present study, our results showed that TERT might be a potential biomarker for tumour recurrence." (PMID 37892022, 2023). "We hypothesize, that TERT-amplified patients should receive surgical resection despite the early pT tumor stage." (PMID 37848472, 2023). "Interestingly, we found that TERT deficiency in the tumor microenvironment decreased TERT activity and expression in LLC tumor samples as compared with telomerase proficient microenvironment." (PMID 37085672, 2023). "Thus, inhibiting TERT/telomerase in tumor cells or promoting the expression of its antagonist are reasonably effective treatment designs." (PMID 37008065, 2023). "Furthermore, the reactivation of the TERT andor ALT pathways, critical for maintaining tumor telomeres, has been biologically linked to glycolysis." (PMID 38090478, 2023). "Named based on the expression of previously established marker genes ERBB2 (T062), NTRK1 (T063), MYCN (T064) and TERT (T065), these subtypes may be rooted in the tumor’s lineage." (PMID 36932241, 2023). "The limitations of the study are the lack of molecular analyses of the tumours such as BRAF or TERT mutations, as these analyses were not routinely performed during the study period and not included in the Swedish national guidelines." (PMID 37099203, 2023). "Importantly, the TERT amplification status was revealed as an indicator of compromised overall survival among patients with a pT1N0-3 tumor stage (median OS: 15.0 vs. 181.8 months, p = 0.006)." (PMID 37848472, 2023). "On the other hand, TERT deficiency and dysfunctional telomeres increased DNA and telomeric damage, cell cycle arrest and apoptosis, and reduced proliferation upon LLC and H358 challenges, contributing to a reduced tumor growth." (PMID 37085672, 2023). "It is interesting that TERT-promoter mutation in the SHH subtype was associated with a higher overall survival rate and lower incidence of tumor metastasis, while group 4 MB patients with TERT-promoter mutation had lower overall survival rates than those with TERT-promoter wild-type." (PMID 36937322, 2023). "A univariate PFS analysis revealed that high tumor infiltration of B cells, CD4 T cells, and CD8 T cells was significantly associated with improved PFS (P < 0.05), and a similar trend was observed in patients with high TERT expression level (P = 0.079)." (PMID 36909826, 2023). "Moreover, the tumour sample T10 was the only sample that presented three potential driver mutations: BRAF, ZFHX3 and telomerase reverse transcriptase (TERT) promoter." (PMID 37317665, 2023). "Specifically, MIBC patients harboring this TERT mutation before RC and/or four months later were at higher risk of tumor progression than those patients without this mutation at these follow-up time points (HR 5.761, p = 0.012)." (PMID 38068899, 2023).
tumor (continued). "The multivariate regression showed that a model using expression of TPO and NIS, mutation status of the TERT promoter, high-risk histology (tall cell PTC, PDTC and DHGTC) and tumour tissue localisation (primary tumour/lymph node) performed very well in predicting iodine avidity." (PMID 37352166, 2023). "Notably, TERT deficiency and dysfunctional telomeres reduced peripheral IL6 and TNF levels, as well as expression of inflammation and tumor immunosuppression markers Tnf, Ifng, IL10 and PD-1 upon LLC challenge." (PMID 37085672, 2023). "In tumours from the 34 patients with a TERT 5’UTR mutations, there were no overlapping unclassified/tandem-duplication events or a SV deletion/unclassified promoter breakpoints; an observation consistent with earlier findings." (PMID 38106039, 2023). "A role for TERT in angiogenesis was first described in tumours." (PMID 37041671, 2023). "Increased expression of TERT has been reported in a number of tumor types." (PMID 37372381, 2023). "In PTC, TERT promoter mutations were significantly associated with sex, age, tumor size, vascular invasion, extrathyroidal extension, lymph node and distant metastases, persistence/recurrence, and disease-specific mortality." (PMID 37859987, 2023). "There was no obvious difference in the primary tumor thickness between metastatic samples with vs. without TERT promoter mutations (Wilcoxon p = 0.508)." (PMID 37418389, 2023). "Variable frequencies of TERT promoter mutations have been detected in diverse tumour types of the lower genital tract, associated or not with human papillomavirus infection." (PMID 38033865, 2023). "Similarly, it is worth noting the existence of other pathways able to promote TERT expression during tumor, such as amplifying the TERT gene, hypermethylation of the promoter, and chromosomal rearrangement." (PMID 36810441, 2023). "TERT mutation conferred increased mortality (HR 2.16 (1.20–3.88), p = 0.01) when detected in plasma (adjusted HR 2.16 (1.20–3.88), p = 0.010), but not in tumor (adjusted HR 1.11 (0.35–3.56), p = 0.860)." (PMID 37762533, 2023). "Therapeutic treatments that target telomerase in tumours have been challenging, as some healthy somatic cells express very low levels of telomerase activity (e.g. lymphocytes) and key components of telomerase (e.g. TERT/TERC) are ubiquitously expressed." (PMID 37041671, 2023). "It has been demonstrated that PI3K/Akt/c-Myc pathway regulates TERT expression in tumour cells." (PMID 36938425, 2023). "During his recovery, molecular testing on the biopsy reported a ROS1 fusion identified by fluorescence in situ hybridization (FISH), and next-generation sequencing (NGS) of tumor DNA identified a KRAS p.G12C mutation and a telomerase reverse transcriptase (TERT) promoter mutation (c.-124C>T)." (PMID 36690705, 2023). "However, TERT expression and telomerase activity are reactivated during tumorigenesis and tumor progression and are considered to be biomarkers of tumor cells." (PMID 37575241, 2023). "Furthermore, a unique TERT/Apollo/HSP70 complex appears to protect the telomeres in neoplasms, which should be investigated in healthy tissues." (PMID 37041671, 2023). "Furthermore, the systemic anti-TERT Th1 response drives robust possessive anti-tumor activity in NSCLC." (PMID 38328405, 2023). "The mRNA expression of TERT was studied in the same tumor samples (n = 19 samples available)." (PMID 37296851, 2023). "On the other hand, the plasma sHLA-G is frequently undetectable/low in PTC patients, and its levels were not influenced by any of the assessed markers in the tumor microenvironment (BRAF or HLA-G tumor expression, BRAFV600E, and TERT mutations), as reported in this series." (PMID 37569841, 2023). "Tumor immune signatures are estimated to elucidate the role of TERT during tumor rejection." (PMID 37418389, 2023).
tumor (continued). "After confirmation of the utility of HP [1-13C]6PG for assessing TERT expression in live cells, our next step was to assess whether we could observe changes in TERT expression after TERT or GABPB1 targeting in preclinical in vivo tumor models." (PMID 36997627, 2023). "As most of the patients whose samples were used for NGS exhibited advanced stages of the disease with aggressive tumor behavior, we did not compare the prognostic differences between the patients with and without TERT promoter mutations in the present study." (PMID 35135543, 2022). "Zhang et al26 reported that the overexpression of hsa_circ_0020397 in CRC cells could promote expression of TERT and PD‐L1, which contribute to immunocyte exhaustion and tumour escape from immune responses by sponging miR‐138." (PMID 33277969, 2022). "Determining how EGFR upregulates TERT specifically from the mutant TERTp is, therefore, critical for understanding the potential interaction between oncogene signaling, cell proliferation, and tumor cell immortality at the molecular level." (PMID 36130485, 2022). "19q), a transcriptional repressor, which in consequence promotes proliferation, blocks differentiation and, in combination with activating mutations in the promoter of the TERT-gene, supporting survival of IDH-O tumour cells via a telomerase-driven telomere maintenance mechanism (TEL-TMM)." (PMID 35681780, 2022). "There were 5 TERT mutation positive samples, 3 primary tumors without relapse, and a primary-relapse tumor pair from one patient, and 18 cases were wild type for the TERT mutation." (PMID 35723333, 2022). "Intriguingly, the presence of TERT promoter mutations represents a featured hallmark for aggressive TCs whereas GABPA and GABPB1 expression is downregulated in those tumours." (PMID 36394204, 2022). "We described noncanonical functions of TERT several years ago, including the induction of cell gene expression, and decided to explore whether TERT/TERT may play a role in tumor progression beyond its function in cell immortalization." (PMID 35437795, 2022). "In addition, the LOH of CDKN2A, a critical tumor suppressor gene and senescence effector, occurred in one subline of TERT-NHUCs, while its promoter hypermethylation was more frequent and led to silent CDKN2A expression." (PMID 36713366, 2022). "Results suggest that the wild-type genotype of TERT Rs2736100 may be a protective factor for lymph node metastasis and histological pattern of tumor invasion in LSCC." (PMID 36415512, 2022). "One study compared the presence of TERT mutation in ctDNA and corresponding tumor tissue, and found that non-concordance (ctDNA-, tissue+) was associated with an early TNM stage." (PMID 35311090, 2022). "Among the 24 patients with integration in the tumor, we found that a significant proportion of the integrations, especially those in the hotspot regions around TERT and KMT2B (MLL4), were often truncal events that happened in the early history of tumorigenesis." (PMID 35382356, 2022). "Notably, 50% of clinically aggressive tumours (21/42) of our series were positive for TERT promoter methylation as they exceeded the 16.1% cut‐off." (PMID 35979662, 2022). "This association was observed in G2/3 (IDH1 vs IDH2: p = 7e−6) but not in DD CS (IDH1 vs IDH2: p > 0.99), implying that although TERT is associated with high-grade tumours, this is not equal in the context of IDH mutation status." (PMID 36042521, 2022). "Because somatic mutation of TERT promoter and FGFR3, which were identified in the normal urothelium, have been reported as frequent mutations in tumor tissues by The Cancer Genome Atlas (TCGA), these mutations were thought to be potential drivers in the tumor formation of LG or HG NMIBC." (PMID 36198773, 2022). "On the other hand, tumour‐lymphocytic infiltrates could lead to a misinterpretation of TERT expression results in some particular cases, as this cell lineage can maintain TERT expression after differentiation." (PMID 35979662, 2022).
tumor (continued). "Moreover, loss of tumor suppressor can also be seen in benign Spitz tumors, suggesting that other somatic alterations, such as the more-common mutations of the TERT promoter or the overall mutational burden, may be better markers of clinical outcomes for these patients." (PMID 36017742, 2022). "Specifically, analysis of extensive tumor collections confirmed the prevalence of three key mutational driver types in HR-NB, namely MYCN amplification, ATRX inactivation, and rearrangement of the TERT promoter." (PMID 36030273, 2022). "The telomerase reverse transcriptase (TERT)-positive tumor treated with CCL20/IL15-armed oAd that replicated under control of the TERT promoter plus NK showed significantly higher antitumor efficacy than either of the treatments alone and induced tumor-specific cytotoxicity of CTLs." (PMID 36091031, 2022). "The TERT mutation detected in plasma was associated with increased mortality (adjusted HR 2.16 [1.20–3.88], p = 0.10), but not in tumor tissue (adjusted HR 1.11 [0.35–3.56], p = 0.86)." (PMID 35159010, 2022). "Among the nine TERT expressing tumours negative for promoter mutations and methylation, six corresponded to patients with excellent response to the primary treatment with a median follow‐up of 120 months (72–144‐month range)." (PMID 35979662, 2022). "TERT-based vaccines or immunotherapy have been applied for the treatment of several solid tumors with high rates of specific immune responses and improved tumor microenvironment." (PMID 36713366, 2022). "Interestingly, profiling of the left-sided tumor manifestation revealed a fundamentally different profile: This tumor showed IDH1 and IDH2 wildtype and TERT C228T promoter mutation." (PMID 35018523, 2022). "TERT mRNA levels were >50‐fold higher in these two tumours compared to the remaining 7 tumours." (PMID 36394204, 2022). "The molecular mechanisms of TERT upregulation are complex, tumor subtype specific and may be clinically relevant." (PMID 35563554, 2022). "However, as this tumor harbored a TERT rearrangement and high TERT expression, we considered this case as TEL[+]." (PMID 36153564, 2022). "TERT promoter status is generally stable between primary and recurrent tumor tissues in adult-type diffuse gliomas and plays an important role in the very early stages of tumor development in GBMs." (PMID 36614997, 2022). "The TERT gene is expressed in TC tumours with and without TERT promoter mutations, and theoretically, as a TC diagnostic marker improves sensitivity." (PMID 36394204, 2022). "In fact, this feature could explain the positivity of TERT expression of most of the tumours in our series with an exceptional response to primary treatment, and without other molecular or clinical evidence related to poor prognosis." (PMID 35979662, 2022). "The TERT promoter provides preliminary validation of the potential tumor treatment." (PMID 35053139, 2022). "TERT has been widely studied in cellular senescence and tumor research." (PMID 36299510, 2022). "In tumor cells, mutant TERT promotes cell proliferation and invasion by inhibiting cell apoptosis." (PMID 35053139, 2022).